PNLIPRP1 (pancreatic lipase related protein 1)
Description:
In vitro, it has very low or undetectable lipase activity towards triglycerides, diglycerides, phosphatidylcholine, galactolipids or cholesterol esters (By similarity). Unable to hydrolyze milk fat (in vitro).
Synonyms: PLRP1
Tractability: Small molecule: it belongs to a druggable protein family. Antibody: UniProt places it where antibodies can reach, with high confidence; its Gene Ontology location is reachable by antibodies, with high confidence; UniProt predicts a signal peptide or a membrane-spanning region.
Gene: Protein-coding gene on chromosome 10 (116,590,385 to 116,609,175, forward strand). Ensembl gene ENSG00000187021.
Subcellular location: Secreted
Pathways (Reactome):
Digestion and absorption: Digestion of dietary lipid
Gene Ontology:
Molecular function: lipase activity; protein binding; calcium ion binding; lipoprotein lipase activity; phospholipase A1 activity; triacylglycerol lipase activity; carboxylic ester hydrolase activity
Biological process: cholesterol homeostasis; fatty acid biosynthetic process; high-density lipoprotein particle remodeling; triglyceride catabolic process; lipid metabolic process
Cellular component: extracellular region
Genetic constraint (gnomAD): Loss-of-function variants: 40 observed, 39.32 expected, observed/expected ratio (o/e) 1.02, 90% interval 0.79 to 1.32. The upper end of that interval is the gene's LOEUF score, 1.32, which puts it in group 5 of 6, group 1 being the genes least tolerant of losing a copy. Missense variants: 410 observed, 435.97 expected, observed/expected ratio (o/e) 0.94, 90% interval 0.87 to 1.02. Synonymous variants: 167 observed, 161.57 expected, observed/expected ratio (o/e) 1.03, 90% interval 0.91 to 1.17.
Homologues: Orthologues: macaque PNLIPRP1 (97% identical), mouse Pnliprp1 (84% identical), pig PNLIPRP1 (84% identical), rabbit PNLIPRP1 (83% identical), dog PNLIPRP1 (83% identical), rat Pnliprp1 (81% identical), Drosophila melanogaster CG6847 (28% identical), Drosophila melanogaster CG13282 (25% identical), Drosophila melanogaster CG7367 (25% identical), Drosophila melanogaster CG6472 (24% identical), Drosophila melanogaster CG34447 (24% identical), Drosophila melanogaster CG34448 (24% identical), and 20 more. Paralogues in human: PNLIP (67% identical), PNLIPRP2 (63% identical), PNLIPRP3 (49% identical), LIPC (30% identical), LIPG (28% identical), LIPH (27% identical), LPL (27% identical), LIPI (26% identical), PLA1A (24% identical).
Diseases named in the same sentence as PNLIPRP1 in open-access papers:
PNLIPRP1 is named in the same sentence as 11 diseases in open-access papers, as found by Europe PMC text mining. Sharing a sentence is not in itself a finding about the gene and the disease. The quoted sentences say what the papers report.
pancreatic cancer (2 papers, 2010 to 2024). "PNLIPRP1 is pancreatic lipase related protein that is important in lipid metabolic process and low levels of this gene has been implicated in pancreatic cancer." (PMID 39120880, 2024).
cholesterol metabolism disorders (1 paper, 2025). "Previous studies showed that the genetic variants of the PNLIPRP1 gene were associated with human carbohydrate and cholesterol metabolism disorders." (PMID 39857271, 2025).
Constipation (1 paper, 2024). Infrequent or difficult evacuation of feces. "The present results suggest that C3 deficiency-induced constipation may be associated with 1237 upregulated genes including PNLIP, CEL, CPB1, CTRL, PNLIPRP1, and REG1 as well as 1292 downregulated genes including Eif2s3y, UTY, KDM5D, IGKV6-32, Olfr870, and DDX3Y." (PMID 39273477, 2024).
COVID-19 (1 paper, 2023). A disease caused by infection with severe acute respiratory syndrome coronavirus 2. "Transcription of the pancreatic lipase related protein 1 (PNLIPRP1) was enhanced in COVID-19 cases vs. controls (FC = 0.98, FDR = 0.25 in virus-positive; FC = 1.46, FDR = 0.17 in virus-negative tissues)." (PMID 37246981, 2023).
Type 1 diabetes (1 paper, 2025). "We show colocalization of pQTLs for CTRB1, APOBR, IL7R, CPA1, and PNLIPRP1 with Type 1 diabetes GWAS signals, and Mendelian randomization causally implicates each of these five proteins in the aetiology of Type 1 diabetes." (PMID 40263317, 2025).
tumor (2 papers, 2016 to 2019). "PNLIPRP1 and GNMT have been documented as the tumor suppressor genes of PC and PHGDH been certified as the tumor promoter gene of PC." (PMID 31706267, 2019).
PNLIPRP1 also shares sentences with these, for which no sentence is quoted: cancer (2 papers); colonic neoplasm (1); colorectal cancer (1); gastrointestinal tumors (1); prostate carcinoma (1).